COL19A1 (collagen type XIX alpha 1 chain)
Description:
May act as a cross-bridge between fibrils and other extracellular matrix molecules. Involved in skeletal myogenesis in the developing esophagus. May play a role in organization of the pericellular matrix or the sphinteric smooth muscle.
Synonyms: COL9A1L; D6S228E
Tractability: Antibody: its Gene Ontology location is reachable by antibodies, with high confidence; UniProt places it where antibodies can reach, with medium confidence; UniProt predicts a signal peptide or a membrane-spanning region.
Gene: Protein-coding gene on chromosome 6 (69,866,556 to 70,212,468, forward strand). Ensembl gene ENSG00000082293.
Subcellular location: Secreted, extracellular space, extracellular matrix
Pathways (Reactome):
Extracellular matrix organization: Collagen biosynthesis and modifying enzymes; Collagen chain trimerization; Collagen degradation
Gene Ontology:
Molecular function: extracellular matrix structural constituent; extracellular matrix structural constituent conferring tensile strength; protein-macromolecule adaptor activity
Biological process: cell adhesion; cell-cell adhesion; extracellular matrix organization; skeletal system development
Cellular component: extracellular matrix; collagen trimer; collagen type XIX trimer; endoplasmic reticulum lumen; extracellular region
Genetic constraint (gnomAD): Loss-of-function variants: 98 observed, 132.25 expected, observed/expected ratio (o/e) 0.74, 90% interval 0.63 to 0.88. The upper end of that interval is the gene's LOEUF score, 0.88, which puts it in group 3 of 6, group 1 being the genes least tolerant of losing a copy. Missense variants: 1,068 observed, 1,123.1 expected, observed/expected ratio (o/e) 0.95, 90% interval 0.9 to 1. Synonymous variants: 411 observed, 370.2 expected, observed/expected ratio (o/e) 1.11, 90% interval 1.02 to 1.21.
Homologues: Orthologues: chimpanzee COL19A1 (99% identical), macaque COL19A1 (97% identical), dog COL19A1 (88% identical), rabbit COL19A1 (87% identical), pig COL19A1 (85% identical), mouse Col19a1 (83% identical), rat Col19a1 (83% identical), guinea pig COL19A1 (81% identical), tropical clawed frog col19a1 (61% identical). Paralogues in human: COL8A1 (24% identical), COL8A2 (23% identical), COL10A1 (22% identical), OTOL1 (10% identical), C1QTNF9 (7% identical), C1QTNF9B (7% identical), C1QTNF2 (6% identical), C1QL1 (5% identical), C1QC (5% identical), C1QTNF3 (5% identical), C1QTNF7 (5% identical), C1QB (5% identical), and 11 more.
Diseases named in the same sentence as COL19A1 in open-access papers:
COL19A1 is named in the same sentence as 17 diseases in open-access papers, as found by Europe PMC text mining. Sharing a sentence is not in itself a finding about the gene and the disease. The quoted sentences say what the papers report.
amyotrophic lateral sclerosis (4 papers, 2020 to 2025). Amyotrophic lateral sclerosis (ALS) is a neurodegenerative disease characterized by progressive muscular paralysis reflecting degeneration of motor neurons in the primary motor cortex, corticospinal tracts, brainstem and spinal cord. "Among those, the COL19A1 gene is rarely expressed by cancer cells but is highly expressed in amyotrophic lateral sclerosis." (PMID 37005910, 2023). "Moreover, COL19A1 is considered to be a potential genetic biomarker of longevity in mice with Amyotrophic Lateral Sclerosis." (PMID 39823074, 2025). "High COL19A1 expression also correlates with poor prognosis in Amyotrophic Lateral Sclerosis (ALS)." (PMID 36516485, 2022).
esophageal squamous cell carcinoma (2 papers, 2023 to 2024). Esophageal squamous cell carcinoma (ESCC) is a type of esophageal carcinoma (EC) that can affect any part of the esophagus, but is usually located in the upper or middle third. "COL19A1 is an alpha chain of type XIX collagen found to be related to immunotherapy response in esophageal squamous cell carcinoma." (PMID 39239354, 2024). "A flowchart of the study showed that high COL19A1 expression conferred a good prognosis for esophageal squamous cell carcinoma (ESCC) patients, and it was also a novel biomarker for successful immunotherapy." (PMID 37005910, 2023).
Anxiety (1 paper, 2023). Intense feelings of nervousness, tension, or panic often arise in response to interpersonal stresses. "We first tested how mutant mice globally lacking Collagen XIX (Col19a1–/–) [Mice have no motor activity and anxiety-related phenotypes] performed in this pheromone preference assay." (PMID 37091919, 2023).
cardiac ischemia (1 paper, 2022). "Recent reports of collagen type XIX (encoded by Col19a1) expression in adult heart and evidence of its enhanced expression in cardiac ischemia suggest important functions for this FACIT in cardiac ECM structure and function." (PMID 35346795, 2022).
Duchenne muscular dystrophy (1 paper, 2014). Duchenne muscular dystrophy (DMD) is a neuromuscular disease characterized by rapidly progressive muscle weakness and wasting due to degeneration of skeletal, smooth and cardiac muscle. "COL19A1 encodes for the alpha-1 chain of collagen XIX which we have found similarly over-expressed in various dystrophies including Duchenne muscular dystrophy (unpublished observation) and probably reflects the amount of fibrosis observed in the muscle biopsies of these patients." (PMID 24484525, 2014).
endometrial cancer (1 paper, 2023). Primary or metastatic malignant neoplasm involving the endometrium (mucous membrane that lines the endometrial cavity). "Overexpression of collagen-associated genes (COL4A4, COL19A1, COL6A6) occurs in the late stages of endometrial cancer, which could indicate that they partake in the progression of EC." (PMID 36982551, 2023).
lung carcinoma (1 paper, 2020). "To support the relevance of type XIX collagen in lung cancer, we investigated the COL19A1 gene expression levels in normal lung and lung cancer using publicly available data from The Cancer Genome Atlas (TCGA) and Genotype-Tissue Expression (GTEx) initiatives." (PMID 32527017, 2020).
schizophrenia (1 paper, 2017). A major psychotic disorder characterized by abnormalities in the perception or expression of reality. "Taken together, the loss of axo-somatic inhibitory synapses in col19a1−/− mutant mice and schizophrenic patients suggests a possible mechanism of how mutation, reduction or complete loss of collagen XIX may contribute to schizophrenia." (PMID 28090790, 2017).
Stomach Adenocarcinoma (1 paper, 2020). "Intersecting prognostic genes with those with high or medium protein staining in at least 50% of the samples, for example, identifies a noticeable gene for HNSC (COL19A1) and one for Stomach Adenocarcinoma (STAD, LGALS4)." (PMID 33266472, 2020).
tumor (3 papers, 2009 to 2019). "Recently, the anti-tumor properties of COL19A1 in vitro have also been described, albeit it is involved in the differentiation of muscle cells, central nervous system development, and formation of the esophagus." (PMID 31011479, 2019). "We found that the expression levels of seven integrin ligands (COL4A6, COL13A1, FGB, COL19A1, COL18A1, COL14A1, and COL11A2) were negatively correlated with the Gleason score, suggesting that the suppression of integrins and/or their ligands is associated with more advanced tumor grade." (PMID 19653896, 2009).
COL19A1 also shares sentences with these, for which no sentence is quoted: cancer (4 papers); Atrophy (1); autism (1); mitral valve disease (1); Myocardial fibrosis (1); neuroblastoma (1); renal fibrosis (1).